CD300A (CD300a molecule)
Description:
Inhibitory receptor which may contribute to the down-regulation of cytolytic activity in natural killer (NK) cells, and to the down-regulation of mast cell degranulation. Negatively regulates the Toll-like receptor (TLR) signaling mediated by MYD88 but not TRIF through activation of PTPN6.
Synonyms: CLM-8; CMRF35-H9; IgSF12; IRp60; CMRF35H; CMRF-35-H9; IRC1; IRC2; CMRF-35H; CMRF35-H; CMRF35H9; IRC1/IRC2
Tractability: Small molecule: it has a high-quality binding pocket. Antibody: UniProt places it where antibodies can reach, with high confidence; its Gene Ontology location is reachable by antibodies, with high confidence; UniProt predicts a signal peptide or a membrane-spanning region; the Human Protein Atlas places it where antibodies can reach. PROTAC: ubiquitination databases record sites on it; its protein half-life has been measured.
Gene: Protein-coding gene on chromosome 17 (74,466,399 to 74,484,798, forward strand). Ensembl gene ENSG00000167851.
Subcellular location: Cell membrane
Subcellular location (Human Protein Atlas): Plasma membrane; Cytosol; Vesicles
Pathways (Reactome):
Immune System: Immunoregulatory interactions between a Lymphoid and a non-Lymphoid cell; Neutrophil degranulation
Disease: Dengue Virus Attachment and Entry
Gene Ontology:
Molecular function: phosphatidylethanolamine binding; phosphatidylserine binding; protein binding; signaling receptor activity; transmembrane signaling receptor activity
Biological process: intracellular signal transduction; negative regulation of B cell proliferation; negative regulation of B cell receptor signaling pathway; negative regulation of eosinophil activation; negative regulation of eosinophil migration; negative regulation of fibroblast proliferation; negative regulation of MAP kinase activity; negative regulation of mast cell activation involved in immune response; negative regulation of mast cell degranulation; negative regulation of MyD88-dependent toll-like receptor signaling pathway; negative regulation of neutrophil activation; negative regulation of NK T cell activation; negative regulation of phagocytosis, engulfment; regulation of T cell receptor signaling pathway; regulation of innate immune response; signal transduction
Cellular component: extracellular exosome; membrane; ficolin-1-rich granule membrane; plasma membrane; tertiary granule membrane
Genetic constraint (gnomAD): Loss-of-function variants: 22 observed, 33.71 expected, observed/expected ratio (o/e) 0.65, 90% interval 0.47 to 0.93. The upper end of that interval is the gene's LOEUF score, 0.93, which puts it in group 3 of 6, group 1 being the genes least tolerant of losing a copy. Missense variants: 326 observed, 369.74 expected, observed/expected ratio (o/e) 0.88, 90% interval 0.81 to 0.97. Synonymous variants: 136 observed, 152.59 expected, observed/expected ratio (o/e) 0.89, 90% interval 0.77 to 1.03.
Homologues: Orthologues: chimpanzee CD300A (96% identical), macaque CD300A (84% identical), guinea pig CD300A (56% identical), mouse Cd300a (42% identical). Paralogues in human: CD300C (45% identical), CD300H (28% identical), CD300E (26% identical), CD300LF (26% identical), CD300LG (22% identical), CD300LD (22% identical), CD300LB (21% identical), FCMR (20% identical), FCAMR (17% identical), TREM2 (16% identical), PIGR (16% identical), TREML1 (15% identical), and 1 more.
Diseases named in the same sentence as CD300A in open-access papers:
CD300A is named in the same sentence as 53 diseases in open-access papers, as found by Europe PMC text mining. Sharing a sentence is not in itself a finding about the gene and the disease. The quoted sentences say what the papers report.
Allergy (5 papers, 2020 to 2025). An allergy is an immune response or reaction to substances that are usually not harmful. "This bispecific antibody potently suppressed mast cell degranulation via FcεRI and demonstrated the potential therapeutic usefulness of targeting CD300a on mast cells in regulating allergies and immunity." (PMID 40507267, 2025). "This would be supported by the fact that in other diseases with an important inflammatory component, such as allergy, psoriasis or ulcerative colitis, CD300a indeed decreases the inflammatory state." (PMID 39020346, 2024). "In conclusion, and considering the overall increased skin inflammation observed in AD-induced CD300a−/− mice, a down-regulatory role for CD300a was suggested, not only in AD but also in other allergic diseases." (PMID 32365988, 2020). "Briefly, CD300a has been shown to downregulate mast cells, eosinophils and basophils effector functions, thereby serving as a potential target for inhibiting allergic effector cells input in allergy." (PMID 32365988, 2020). "We have previously characterized CD300a role on MCs and in vivo in mouse models of allergy, in which the absence of CD300a resulted in increased inflammatory features and delayed resolution." (PMID 36928079, 2023).
asthma (4 papers, 2008 to 2022). "Moreover a bi-specific Ab to CD300a and IgE inhibited acute airway inflammation in an experimental asthma mouse model and passive cutaneous anaphylaxis." (PMID 22876248, 2012). "This Ab has also been seen to act against tissue inflammation and remodeling in a murine model of chronic experimental asthma, demonstrating that a specific targeting of CD300a in CCR3-positive cells may be a potent tool for treating airway inflammation and tissue remodeling." (PMID 32365988, 2020). "Also a bi-specific Ab against CD300a and CCR3 inhibited chronic airway inflammation in murine asthma, possibly by its binding on both MC and eosinophils and their consequent inhibition." (PMID 22876248, 2012).
diffuse large B-cell lymphoma (4 papers, 2015 to 2025). "In addition, CD300a triggering has been linked to immune escape, and poor prognosis in certain cancers (e.g., glioblastoma, and diffuse large B cell lymphoma), and may be stage specific in other models." (PMID 40507267, 2025). "In an analysis of public dataset, we found that CD300A mRNA levels were inversely correlated with the overall survival time of patients with diffuse large B-cell lymphoma (DLBCL)." (PMID 26435477, 2015). "In diffuse large B-cell lymphoma (DLBCL), high CD300a expression correlates with poor prognosis and increased tumorigenicity." (PMID 40507267, 2025).
viral infections (4 papers, 2017 to 2023). "Regarding B cells, besides some aspects of the expression and function of CD300a on several human B cell subsets, its relevance in B cell leukemogenesis, and its potential relevance in viral infections, its role is not completely known." (PMID 37762055, 2023). "CD300a has an important role in some viral infections and its expression levels are known to be modulated by human immunodeficiency virus (HIV)−1 infection on several cell types." (PMID 32269232, 2020). "In this context, it has been shown that the interaction of CD300a with PS and PE enhances the infection of Dengue virus and other mosquito-borne viruses such as Yellow fever, West Nile, and Chikungunya viruses." (PMID 30083165, 2018). "All these data supports that CD300a has an inhibitory role and it is important for viral infections." (PMID 28626460, 2017). "Among others, CD300a has been related to bacterial, parasitic, and viral infections." (PMID 37762055, 2023).
acute myeloid leukemia (3 papers, 2018 to 2025). Acute myeloid leukemia (AML) is a group of neoplasms arising from precursor cells committed to the myeloid cell-line differentiation. "In addition to its established roles in hematologic malignancies—including chronic lymphocytic leukemia, acute lymphoblastic leukemia, and acute myeloid leukemia—CD300a has also been implicated in modulating tumor-associated immune responses in other pathological contexts." (PMID 40507267, 2025). "CD300A was found to be highly expressed with statistical significance in acute myeloid leukemia (AML), as well as associated with prognosis, through the analysis of differential expression genes using the TCGA and GTEx database." (PMID 29938007, 2018). "CD300a may contribute to tumor progression in hematologic malignancies, particularly in acute myeloid leukemia (AML)." (PMID 40507267, 2025). "Regarding acute myeloid leukemia (AML), CD300A (a type I transmembrane protein) is expressed in the myeloid cells." (PMID 35832555, 2022).
breast carcinoma (3 papers, 2017 to 2025). "In the 4T1 murine breast cancer model, smaller tumors were observed in CD300a knockout mice compared to wild-type controls, along with a signifi-cant increase in mast cell activation." (PMID 40507267, 2025). "Blockade of CD300a alone has demonstrated significant anti-tumor efficacy in preclinical breast cancer models, supporting its potential as a standalone immunotherapeutic strategy." (PMID 40507267, 2025). "In a breast cancer model, CD300a was shown to suppress mast cell–mediated anti-tumor responses by binding to PS and PE, which are enriched on tumor cell membranes." (PMID 40507267, 2025). "Treatment with a blocking anti-CD300a antibody significantly suppressed tumor growth in a murine 4T1 breast cancer model, accompanied by robust activation of immune cells in the TME, such as mast cells and T cells." (PMID 40507267, 2025).
dengue (3 papers, 2020 to 2025). "Overall, our results show that B cells are susceptible to direct infection by DENV of B cells through CD300a, and the responses of B cells to the infection could play a role in pathogenesis of dengue." (PMID 33643283, 2020). "To summarize, our results show that B cells are susceptible to direct infection by DENV via CD300a and the subsequent B cell responses could contribute to dengue pathogenesis." (PMID 33643283, 2020). "Despite reducing phagocytosis of apoptotic materials, CD300a enhances entry of dengue in 293T cells, and CD300a antibodies could partially inhibit dengue uptake into macrophages." (PMID 41020590, 2025).
acute lymphoblastic leukemia (2 papers, 2018 to 2023). Leukemia with an acute onset, characterized by the presence of lymphoblasts in the bone marrow and the peripheral blood. "In another research, patient-derived acute lymphoblastic leukemia (ALL) cells expressed CD300A at high levels compared to normal pre-B cells and the patients with high CD300A levels showed worse OS compared to the others." (PMID 29938007, 2018).
HIV-1 infection (2 papers, 2018 to 2020). The type species of lentivirus and the etiologic agent of acquired immunodeficiency syndrome (AIDS). "Nevertheless, given the high percentage of HIV-1+ patients that are co-infected with CMV49,50, further studies are required to determine the role of CMV infection on the regulation of CD300a expression in HIV-1 infection." (PMID 32269232, 2020). "The relationship between HIV-1 infection progression markers and CD300a expression was studied in order to investigate the clinical relevance of this cell surface receptor." (PMID 32269232, 2020). "These are encouraging results that hopefully will lead to new research intended to further understand the role of CD300a in CD8+ T cells during HIV-1 infection." (PMID 32269232, 2020). "Next, correlation analyses were carried out between CD300a expression and clinical markers of HIV-1 infection such as CD4+ T cell count and viral load." (PMID 32269232, 2020). "However, there are only a few publications about CD300a on HIV-1 infection." (PMID 30083165, 2018). "Though, as other immunomodulatory receptors such as PD1, the CD300a inhibitory receptor may be inductively expressed after T cell activation as a regulatory mechanism during HIV-1 infection, and probably the cytokine environment has an important role determining the expression levels of CD300a." (PMID 30083165, 2018). "Moreover, we have discovered a negative correlation between CD300a levels and some markers of HIV-1 infection progression in cART naïve HIV-1 infected patients." (PMID 30083165, 2018). "Therefore, our results demonstrated that HIV-1 infection increases CD300a expression levels on CD4+CD300a+ cells and that cART does not reverse the upregulation of CD300a expression found in these patients." (PMID 30083165, 2018).
leukemia (2 papers, 2023 to 2025). A malignant (clonal) hematologic disorder, involving hematopoietic stem cells and characterized by the presence of primitive or atypical myeloid or lymphoid cells in the bone marrow and the blood. "Consistently, we found a significant enrichment of H3K4me3 marks in the promoter regions of CD300A gene in three types of leukemia cells from published ChIP‐seq datasets (K562 cells from GSE74359; MLL‐AF9 blast cells from GSE89336; KG‐1 cells from GSE109619)." (PMID 35642341, 2023). "Overall, these results suggest that, at least in leukemia cells, CD300A expression might be regulated by histone modification." (PMID 35642341, 2023). "Similarly, we observed a significant enrichment of H3K4me3 marks in the promoter regions of CD300A gene in leukemia cell lines." (PMID 35642341, 2023).
nasal polyps (2 papers, 2012 to 2021). "The expression of CD300a and CD300f was shown in MC, where CD300a presents on MC from nasal polyps, lungs, and on hCBMC and its mouse ortholog LMIR-1, is expressed on mBMMC." (PMID 22876248, 2012).
psoriasis (2 papers, 2011 to 2024). An autoimmune condition characterized by red, well-delineated plaques with silvery scales that are usually on the extensor surfaces and scalp. "Furthermore, genetic studies have revealed that a non-synonymous mutation in the CD300a extracellular domain is linked to psoriasis susceptibility and that is implicated in the development of Alzheimer's disease." (PMID 22046970, 2011). "Other studies have shown that circulating CD4+CD45RO+ T cells exhibit lower expression of CD300a/c in psoriasis patients compared with healthy donors." (PMID 22046970, 2011).
Sepsis (2 papers, 2024 to 2025). Sepsis is defined as life-threatening organ dysfunction caused by a dysregulated host response to infection. "These stimuli are known to be present in HLH and, to our best knowledge, this is the first time that CD300a has been analyzed in HLH and sepsis." (PMID 41463121, 2025). "Even though soluble CD300a has not been described to date, to the best of our knowledge, soluble forms for other CD300 members, like CD300b have been found recently, being released by neutrophils in response to lipopolysaccharide (LPS) to amplify lethal inflammation in sepsis." (PMID 39020346, 2024).
B-cell lymphoma (1 paper, 2015). "Similarly, our present study suggested an oncogenic role of CD300A in B-cell lymphoma in which loss of CD300A suppressed DLBCL growth both in vitro and in vivo." (PMID 26435477, 2015).
CMV infection (1 paper, 2017). "In our hands CD57+ T-cells co-expressing CD300a expand with CMV infection (in young individuals), highlighting a relevant role for both makers in the control of CMV virus by T-cells." (PMID 28626460, 2017). "Here, we analyzed, in different T-cell subsets, how age and CMV infection alter the expression of the inhibitory receptors CD300a and CD161 and their relation with the marker CD57, which has been shown to be a polyfunctionality maker of CD4+, CD8+, and NKT-like T-cells." (PMID 28626460, 2017). "Furthermore, CD300a+ DN T-cells increased with CMV infection in young individuals and further increased in old CMV-seropositive individuals." (PMID 28626460, 2017). "Specifically, with CMV infection (young individuals), CD57 is increased only in CD4+ and CD8+ T-cells and CD300a in CD4+ and DN subsets." (PMID 28626460, 2017). "Analysis of CD4+ T-cell subset showed that CD57+CD4+ and CD300a+CD4+ T-cells increased with age in CMV-seropositive individuals and with CMV infection in young individuals." (PMID 28626460, 2017). "The expression of CD57, CD161, and CD300a markers on NKT-like cells was not affected by CMV infection alone." (PMID 28626460, 2017). "NKT-like CD161+ phenotypes (CD57−CD161+CD300a− and CD57−CD161+CD300a+) decreased with age in CMV-seropositive individuals, but not with CMV infection alone." (PMID 28626460, 2017). "Furthermore, the total expression of CD161, contrarily to CD57 and CD300a, decreases with age in CMV-seropositive individuals and is not affected by CMV infection alone in young individuals." (PMID 28626460, 2017).
colitis (1 paper, 2023). Inflammation of the colon. "We have recently shown that the expression of CD300a, CD300b and CD300f were elevated in patients with IBD and that CD300f (but not CD300a) regulates colonic inflammation in response to dextran sodium sulphate (DSS)-induced colitis." (PMID 37033950, 2023). "Furthermore, we have shown that CD300f (but not CD300a) regulates colonic inflammation in response to DSS-induced colitis." (PMID 37033950, 2023).
COVID-19 (1 paper, 2021). A disease caused by infection with severe acute respiratory syndrome coronavirus 2. "Specifically, while the expression levels of CD300a and CD300e increased in monocytes from patients with mild and moderate disease, a drastic decrease was observed in patients with a severe form of COVID-19." (PMID 33777054, 2021). "It is interesting to see how the expression levels of an inhibitory receptor (CD300a) and activating receptor (CD300e) are regulated in the same manner in COVID-19 patients." (PMID 33777054, 2021). "Therefore, we decided to determine the expression of the inhibitory receptor CD300a and activating receptors CD300c and CD300e on monocytes from patients with COVID-19." (PMID 33777054, 2021). "The expression of CD300a in granulocytes (CD66b+ cells) was similar to monocytes, with an increase in patients with mild and moderate disease and then a decline in patients with severe COVID-19." (PMID 33777054, 2021). "However, a change in the pattern of CD300a and CD300e receptors expression happened in patients with severe COVID-19 that exhibited very low levels of these two molecules." (PMID 33777054, 2021). "Therefore, a possible explanation for the decrease in CD300a expression is that the circulating monocytes and granulocytes are more immature (and possibly more dysfunctional) that those observed in mild and moderate COVID-19." (PMID 33777054, 2021).
glioma (1 paper, 2024). A benign or malignant brain and spinal cord tumor that arises from glial cells (astrocytes, oligodendrocytes, ependymal cells). "Furthermore, we could identify several novel glioma biomarkers likely helpful in both diagnosis and prognosis of the patients, including the genes PPP1R8, GPBP1L1, KIAA1614, C14orf23, CCDC77, BVES, EXD3, CD300A, and HEPN1." (PMID 38812741, 2024).
ischemic stroke (1 paper, 2023). A stroke disorder caused by obstruction of blood flow to the brain, due to thrombotic (local blood clot formation) or embolic (due to a blood clot or other material traveling from another site) event. "An anti-CD300a neutralizing antibody also reduced infarction at 24 h after ischemia and ameliorated neurological deficits during the acute phase of ischemic stroke." (PMID 37601043, 2023). "CD300a deletion or CD300a neutralizing antibody attenuates inflammation and ameliorates neurological deficits during the superacute phase of ischemic stroke." (PMID 37601043, 2023).
latent infection (1 paper, 2016). "In conclusion, CMV latent infection has a profound impact on NK cells inducing significant changes in the expression of NK receptors, including the inhibitory receptors CD300a and CD161." (PMID 27872625, 2016). "We analyzed by flow cytometry the expression of CD300a and CD161 inhibitory receptors on NK cells (CD56bright and CD56dim) from healthy individuals stratified by age and CMV latent infection." (PMID 27872625, 2016).
lung carcinoma (1 paper, 2024). "Noteworthy, CD300A overexpression has been found to inhibit progression of NSCLC and decreased expression of CD300LG (> 90% expression decrease) has been reported in lung cancers." (PMID 38704802, 2024).